RNVU1-18 (RNA, variant U1 small nuclear 18)
Synonyms: vU1.18; U1P101; U1P15; U1.15; RNU1-25; RNU1-25P; RNU1-5; RNU1P1; RNU1P9
Gene: Small nuclear RNA gene on chromosome 1 (143,729,407 to 143,729,570, reverse strand). Ensembl gene ENSG00000206737.
Gene Ontology:
Molecular function: pre-mRNA 5'-splice site binding
Biological process: mRNA 5'-splice site recognition
Cellular component: U1 snRNP
Homologues: Orthologues: guinea pig U1 (100% identical). Paralogues in human: RNU1-1 (100% identical), RNU1-2 (100% identical), RNU1-27P (100% identical), RNU1-28P (100% identical), RNU1-3 (100% identical), RNU1-4 (100% identical), RNVU1-29 (100% identical), U1 (100% identical), RNVU1-28 (99% identical), RNVU1-7 (99% identical), RNVU1-31 (99% identical), RNU1-89P (97% identical), and 134 more.
Diseases named in the same sentence as RNVU1-18 in open-access papers:
RNVU1-18 is named in the same sentence as 1 disease in open-access papers, as found by Europe PMC text mining. Sharing a sentence is not in itself a finding about the gene and the disease.
RNVU1-18 shares sentences with these, for which no sentence is quoted: amyotrophic lateral sclerosis (1 paper).